IL6 (interleukin 6)
Diseases named in the same sentence as IL6 in open-access papers (continued):
Sharing a sentence is not in itself a finding about the gene and the disease.
melanoma (continued). "Furthermore, melanoma STAT3 activation (pSTAT3Tyr70) and IL-6 secretion following exposure to ceramides was significantly increased." (PMID 40280124, 2025). "A recent study suggests that cytokine IL-6 could be the biomarker of disease progression and poor prognosis in BRAF wild-type advanced melanoma treated with pembrolizumab." (PMID 39195270, 2024). "IL-6 expression, driven by a newly identified interaction between endogenous E2F1 and active STAT3, leads to massive cytokine secretion via a positive feedback loop, both in melanoma and CD4+ T cells." (PMID 39544930, 2024). "In melanoma, UPR activation catalyzes tumor cell proliferation via the IL-6/STAT3 axis." (PMID 39080273, 2024). "In order to decipher the potential crosstalk that may link TNFα/IL-6 inductions triggered by TH1902 to the increased levels of MHC-I and PD-L1, B16-F10 melanoma cells were treated with the indicated TNFα or IL-6 concentrations for 96 hours." (PMID 38482021, 2024). "V. cinerea extract also significantly inhibited lung tumor formation (by 78.8%) in B16F-10 melanoma cells by suppressing the production and expression of proinflammatory cytokines such as TNF-α, IL-1β, IL-6, and granulocyte-macrophage colony-stimulating factor (GM-CSF)." (PMID 38732642, 2024). "More importantly, our data evidently supported a strong influence of E2F1 and its target IL-6 on the Th1/Th2 development like Th2 cytokine production, downregulation of ERK1/2 pathways, IFN-γ response (bottom), or CCL2 expression in melanoma cells." (PMID 39544930, 2024). "It has been shown that interleukin-6 (IL-6) inhibits the growth of melanocytes and early-stage melanoma cells but has no significant inhibitory effect on late-stage melanoma cells." (PMID 38952546, 2024). "The combination of pharmacologic sEH inhibition and immune checkpoint blockade resulted in decreased gene expression of the pro-inflammatory cytokines Il-6, Cxcl1, Tnfα, Ccl2, and Ccl4 compared to control after 11 d of treatment in the B16F10 melanoma tumor tissue." (PMID 38330013, 2024). "Moreover, we found significant enrichment of pro-inflammatory IL6, TNF, and IFNγ gene sets in macrophages that had taken up melanosomes secreted by MNT1 melanoma cells and in those that had taken up melanosomes from either keratinocytes or fibroblasts." (PMID 38719996, 2024). "The E2F1-STAT3/IL-6 axis strongly modulates the immune niche and generates a crosstalk with CD4+ cells resulting in transcriptional changes of immunoregulatory genes in melanoma and immune cells that is indicative of an inflammatory and immunosuppressive environment." (PMID 39544930, 2024). "Additionally, the proinflammatory cytokine IL-6 is released in the skin following exposure to ultraviolet B (UVB, 280–320 nm) radiation, which is a major factor responsible for the initiation of melanoma development." (PMID 39062529, 2024). "Validation of the pro-inflammatory genes including IL6, TNF, and IL1B revealed a significant increase in their expression in macrophages cultured with melanosomes derived from melanoma cells, keratinocytes, or fibroblasts as compared to naïve macrophages (Fig. EV4A)." (PMID 38719996, 2024). "Pharmacological inhibition of either IRE1α or NF-κB by STF-083010/ MKC8866 and BAY-11-7085 respectively could significantly suppress TG or HA15-induced increased transcription and secretion of both IL-6 and TNF-α in both A2058 and A375 melanoma cell lines." (PMID 38291473, 2024). "Its growth inhibitory effects are mediated by cell cycle G1-arrest associated with DNA damage and induction of apoptosis while other studies on murine melanoma cells showed that piperine treatment significantly reduced proinflammatory cytokines such as TNF-α, IL-1β and IL-6." (PMID 36768978, 2023).
melanoma (continued). "Most secreted factors (TNFα, GM-CSF, G-CSF, PDGF-BB, CCL5, CCL11, IL-3, IL-6) were not induced by exogenous IFNγ in our panel of melanoma cells, confirming the complex inflammatory signaling profile of de-differentiated PD1 PROGs with intrinsic IFNγ signaling." (PMID 36934113, 2023). "IL6 and IL8 also facilitate melanoma cell survival in hypoxia conditions." (PMID 37762344, 2023). "While investigating advanced melanoma patients with high tumor burden, we observed a significant increase in MDSC frequency and suppressive functions as well as in concentration of inflammatory factors in these patients, in particular IL-6 and IL-8." (PMID 36860876, 2023). "In addition—following the in vitro reconstitution of a human melanoma TME using tumor lines (BLM, Mel624 or A375)—PGE2 and IL-6 produced by the tumor transform cDC2s into CD14+ DCs, characterized by an immunosuppressive phenotype." (PMID 37190135, 2023). "Thus, IL-6, IL-10, and TNF-α have been significantly decreased, inhibiting the growth and migration of melanoma cells, suggesting the potential of the two compounds tested to be used as antitumor drugs targeting inflammatory cytokines." (PMID 36829966, 2023). "The high transcriptional IL4I1 expression by MHCII+ CD163− TAMs in MeLiM pigs with regressing melanoma was unexpected, but may result from the enriched IFNγ, TNFα, IL12 and IL6 tumor microenvironment between R0 and R1 stages." (PMID 37526660, 2023). "Enhanced levels of IL-6, TNF-α, and IL-1b in melanoma can trigger an immune response." (PMID 37895833, 2023). "In vitro experiments have demonstrated that MHC class II-expressing melanoma cells can stimulate LAG3+ pDCs to mature and produce IL-6, a finding confirmed in vivo where LAG3+ pDCs displayed elevated IL-6 production and an activated phenotype in close proximity to melanoma cells." (PMID 37569880, 2023). "Other data in preclinical models coupling melanoma with experimental autoimmune encephalitis demonstrate that IL-6 blockade can improve antitumor efficacy without exacerbating autoimmune toxicity." (PMID 36881480, 2023). "Notably, the use of molecules that simultaneously block IL-6 and IL-8 is sufficient to fully inhibit CAF-induced human melanoma cell invasiveness." (PMID 37627054, 2023). "Then, these EVs tended to induce a proinflammatory activation of macrophages by increasing the expression of COX-2 and the release of inflammatory cytokines, such as IL-1β, IL-6, TNF-α, and NO, so as to establish an inflammatory TME which in turn facilitated the progression of melanoma." (PMID 37575250, 2023). "Plasma IL-6 has a negative effect on the survival rate of melanoma patients treated with ICI, and IL-6 appears to be a potential driver of ICI resistance." (PMID 37240834, 2023). "IL-6 levels were measured by ELISA in culture supernatants of naïve (control) melanoma cells, in supernatants of naïve (control) microglia cells, in supernatants of melanoma cells exposed to MGCM, and in supernatants of melanoma-microglia co-cultures." (PMID 37296634, 2023). "In order to further validate these results, we employed the IL-6/JAK/STAT3 pathway inhibitors αIL-6R, Baricitinib (JAK inhibitor, Amadis Chemical) and Stattic (STAT3 Inhibitor, Sigma-Aldrich), and determined their effect on the melanoma-microglia crosstalk." (PMID 37296634, 2023). "Intraperitoneal administration of andrographolide significantly inhibited the B16-F10 melanoma cell line-induced capillary formation in C57BL/6 mice and reduced the levels of pro-inflammatory cytokines, such as IL-1β, IL-6, TNF-α and GM-CSF, and serum NO level." (PMID 36768978, 2023). "In C57BL/6J mice, N. caninum infection was found to induce significant macrophage recruitment to the infection site and increase secretion of interleukin 6 (IL-6), IL-12p40, and interferon gamma (IFN-γ), which was similar to the host immune responses against melanoma." (PMID 36138417, 2022).
melanoma (continued). "Overall, our data provide further support for a role of HGF and MCP-2 as candidate biomarkers of response to ICI in advanced melanoma, while proposing an additive negative effect of these two cytokines, together with IL-6, on response rates." (PMID 36007304, 2022). "On the other hand, the top downregulated genes formed 4 subgroups and were related to melanogenesis (Wnt5a, Mitf, Pomc, Mc1r, Kit), melanoma (Fgf9, Fgf12, Fgf2), MAPK signaling pathway (Ncam1, Prkcb, Map3k4, Pla2g4a, Mapk14, Mapk11), and aging (Tgfbr1, Il6, Nox4)." (PMID 36555664, 2022). "Because we have shown CDDO-Me-mediated attenuation of IL-6 production and STAT3 activation in melanoma-conditioned macrophages, we hypothesize that inhibition of JAK/STAT3 signaling is likely one of the mechanisms by which CDDO-Me inhibits tumor progression." (PMID 35265066, 2022). "Typically, the IL-6 production of adenocarcinoma cell lines (especially MDA and HeLa) was significantly higher than IL-6 secretion of the non-treated or melanoma supernatant-treated DCs." (PMID 36194602, 2022). "Moreover, norepinephrine (NE) is able to upregulate IL-6, IL-8, and VEGF in C8161 the melanoma cell line, exhibiting an autocrine stimulation along with chemotactic and proangiogenic effects, its value being increased in advanced stage melanomas." (PMID 35334544, 2022). "Moreover, EVs reduced the production of different cytokines (IL6, IL10, and IL12) and adhesion factors (sICAM-1, sICAM-3, sPecam-1, and sCD40L) usually secreted by keratinocytes to control melanoma progression." (PMID 35327461, 2022). "In LF cells, synoviocytes, and melanoma cell lines, elastin-derived peptides and/or VGVAPG peptides have been demonstrated to promote the synthesis and/or secretion of inflammatory markers such as IL-1 and IL-6." (PMID 36036007, 2022). "Though Nivolumab did not significantly alter serum cytokine profiles, in melanoma patients we observed a deviation from the physiological range for 7 out 18 cytokines tested: IL-1β, IL-6, CCL2, CXCL8, VEGF, IL-5 and IL-13." (PMID 35173725, 2022). "However, IL6 expression remains dependent on AKT1 and STING, suggesting that the regulation of individual SASP factors in response to CDK4/6 inhibition in melanoma cells is complex, with compensatory mechanisms we have yet to elucidate." (PMID 35158840, 2022). "Another study showed that melanoma-derived exosomes contain VEGF, IL-6, and MMP2." (PMID 35740619, 2022). "Interestingly, these results suggest that the regulatory roles of WNT5A and IL-6 in MARCKS expression and activation are lost during the acquisition of BRAFi resistance in melanoma cells." (PMID 36551563, 2022). "Additionally, we have previously showed that the melanoma-derived lysate TRIMEL induces the release of Th1-polarizing and pro-inflammatory cytokines such as IL-6, TNF-α, and IL-12 in therapeutically used monocyte-derived DCs." (PMID 35805888, 2022). "Epinephrine induces IL-6 in the HCC HepaRG cell line whereas β-ADR activation by norepinephrine mediates its induction in the ovarian cancer lines SKOV3.ip1, Hey-A8, and EG as well as in the melanoma cell lines A375 and Hs29-4T." (PMID 33923958, 2021). "Furthermore, in melanoma, I-BET151 also inhibits the production of cytokines and chemokines, such as IL-1α, VEGFC, IL-6, and IL-8." (PMID 34540687, 2021). "Contrarily, our recent data on the cellular functions of GPR56 in human melanoma cell lines has shown that activation of GPR56 receptor by an immobilized agonistic mAb promoted cell migration and invasion via the production of inflammatory cytokine, IL-6." (PMID 34943858, 2021). "IL-6 and TNF-α secreted by adipocytes block miR-211 expression, leading to the elevated production of TGFβ receptors and, therefore, a phenotypic switch of melanoma from the proliferative to the highly invasive state." (PMID 33430277, 2021). "Anti-IL-6 antibodies abolish STAT3 phosphorylation and block the proliferation of melanoma cells." (PMID 34356855, 2021).
melanoma (continued). "Previous reports showed that cirsiliol induced radio sensitization in non-small cell lung cancer cell lines and inhibited interleukin (IL)-6-incuded STAT3 activation, and that cirsiliol could restrain the colony formation and migration of melanoma cells." (PMID 33731185, 2021). "As expected, IL-6 treatment could significantly rescue CD27-AS1-208 knockdown-induced decrease of colony formation and invasion in melanoma cells." (PMID 35096622, 2021). "IL-6, CRP, and the neutrophil/lymphocyte ratio can be prognostic markers of melanoma." (PMID 34068679, 2021). "The negative effects of IL‐6 on outcomes in cases with PD‐1/PD‐L1 inhibitor use has been shown in a clinical study of patients with melanoma." (PMID 33300678, 2021). "Serum IL-6 and CRP may therefore function as prognostic factors in melanoma patients receiving single agent and combination checkpoint inhibition." (PMID 33924623, 2021). "This difference with respect to regressing melanoma was attributed to the different cytokine microenvironment; in fact, fibrogenic cytokines such as IL-6, TGF-β, TNF-α, bFGF and PDGF are expressed by melanoma while TNF-α, an antifibrogenic cytokine, was found to be more expressed in the halo nevus." (PMID 34300213, 2021). "The IL6-202 and IL6-205 transcripts that confer drug resistance to Vemurafenib by reactivating the MAPK pathway while IL6-201 is not responsible for the resistance in A375 melanoma cells." (PMID 34880901, 2021). "A simultaneous blockade of IL-6 and this signaling led to an increase in the expression of INF-γ produced by CD4+ T cells and consequent enhancement of anti-PD-1 therapy in a mouse model of melanoma." (PMID 34681685, 2021). "Finally, expression of IL6 and CXCL8 was also significantly reduced by stable knockdown of p16 in melanoma cells induced to senesce using etoposide." (PMID 33550279, 2021). "In a first analysis including the entire cohort of recruited patients (in situ and stage I–IV melanoma patients), the amount of GM‐CSF, IL4, IL‐6, IL‐10, IL‐17A, and TGF‐β detected in serum was independent of the age of the melanoma patients and it did not vary between the sexes." (PMID 32485045, 2020). "These in vivo experiments validated our in vitro findings by showing that HDFs with high expression of ATF3 can repress melanoma cell tumor formation and growth, probably through negative regulation of IL-6 production." (PMID 32373541, 2020). "In line with previous findings, early‐stage (I or II) melanoma patients that developed metastasis had significantly higher levels of serum IL‐4 and IL‐6 than patients who did not develop metastasis during the follow‐up." (PMID 32485045, 2020). "In human melanoma cells, spliced XBP1 induces IL-6 expression by directly binding IL-6 promoter." (PMID 32178254, 2020). "Interestingly, some NCDTs under stress begin the production of cytokines as reported recently in human melanoma cell lines under influence of norepinephrine become able to influence tumor progression by modulating the expression of VEGF, IL-8, and IL-6." (PMID 32244473, 2020). "Without this clinical information, rise of S100B and IL-6 would have been interpreted as immune activation against melanoma metastases." (PMID 32188047, 2020). "Interestingly, inflammatory cytokines including IL-6, IL-10, IL-12p70, IFN-γ, TNF-α, MCP-1 and KC were previously shown to be differentially expressed in male and female C57 BL/6J mice in the melanoma model." (PMID 33287312, 2020). "The present study, for the first time, demonstrated that TNF-α and IL-6 secreted by adipocytes could upregulate PD-L1 level in HCC and melanoma." (PMID 32477009, 2020). "Previous studies have shown that BRAF inhibition in melanoma cell lines resulted in a decreased secretion of immunosuppressive factors like IL-10, VEGF, and IL-6 and enhanced expression of melanocyte differentiation antigens (MDA) to improve recognition by MDA-specific T cells." (PMID 31541179, 2020).
melanoma (continued). "Indeed, the levels of IFN-γ, IL-6, KC, VEGF and MCP-1 in the sera of mice injected with melanoma cells both intracutaneously and intravenously were significantly higher in HO-1-deficient than in wild-type mice." (PMID 33287312, 2020). "The upregulation of IL6 with checkpoint blockade was previously characterized in melanoma mice models but not to this current resolution." (PMID 33065980, 2020). "Recently, TNF-α and IL-6 have also been found as regulators of PD-L1 in a variety of cells, however, whether they can regulate PD-L1 expression in HCC or melanoma is unknown." (PMID 32477009, 2020). "Although not the primary focus of this study, we believe that using a blocking IL‐6 Ab and the WNT5A antagonist Box5, which will also restore the sensitivity of BRAFi‐R melanoma cells to BRAFi treatment, is a more relevant therapeutic approach from our perspective." (PMID 30582770, 2019). "However, because the BRAFi‐R melanoma cells secreted much more IL‐6 and expressed more WNT5A, we increased the dose of IL‐6 Ab and Box5 peptide to 2 μg·mL−1 and 200 μm, respectively." (PMID 30582770, 2019). "Furthermore, in a more recent report, we demonstrated that IL‐6 and WNT5A signalling constitute a positive feedback loop that potentiates the migration and invasion of melanoma cells." (PMID 30582770, 2019). "As control, the release of TNFα, IL-6, and IFNγ was also determined for the untreated melanoma cells alone (data not shown)." (PMID 31192129, 2019). "Next, we investigated whether combined inhibition of both IL‐6 and WNT5A signalling had any effect on Cdc42‐GTPase or Rac1‐GTPase activity in BRAFi‐R melanoma cells." (PMID 30582770, 2019). "The question then arises concerning if and how IL‐6 and WNT5A will affect migration and invasion of BRAFi‐R melanoma cells in the absence of an IL‐6/WNT5A positive feedback loop." (PMID 30582770, 2019). "Surprisingly, however, we found that the IL‐6/WNT5A positive feedback loop present in parental melanoma cells was lost during the development of acquired BRAFi resistance, meaning that IL‐6 and WNT5A signalling were independent events in BRAFi‐R melanoma cells." (PMID 30582770, 2019). "Conversely, Linnskog et al37 demonstrated a dose‐dependent increase in Wnt5a expression in IL‐6‐stimulated human melanoma cell lines, HTB63 and A375, whereas Box5, a peptide antagonist of Wnt5a, inhibited IL‐6‐induced cell migration and invasion of the melanoma." (PMID 31313518, 2019). "Our observation of elevated IL‐6 secretion is in accordance with the observation that IL‐6 is not only a promoter of melanoma metastasis but also an inducer of WNT5A protein expression in parental BRAFi‐sensitive melanoma cells." (PMID 30582770, 2019). "The IL-6/JAK1/signal transducer and activator of transcription 3 (STAT3) axis also controls actomyosin contractility by regulating the levels of phosphorylated-MLC2 in both melanoma cells and CAFs." (PMID 31067787, 2019). "Concerning GT genes involved in ganglioside biosynthesis, a functional NFκB binding site at -777/-762 pb upstream the ATG was shown to be essential for ST8SIA1 transcription in melanoma cells and inflammatory cytokines including TNF and IL-6 enhanced GD3S gene expression in melanocytes." (PMID 29698439, 2018). "In addition, CpdA dramatically attenuated TLR4-induced IL-6, IL-8 and XIAP expressions in both MDA-MB-231 BCA and MDA-MB-435 melanoma cells compared to cells with only PTX treatment." (PMID 29486738, 2018). "Although in humans there are extremely sparse studies regarding male versus female IL-6 circulatory concentration and none of them are related to melanoma studies, there are publications that show lower serum values in women compared to men." (PMID 29318162, 2017). "Furthermore, secreted IL-6 functions in an autocrine/paracrine manner, activates the intracellular JAK/STAT3 pathway and promotes the proliferation of melanoma cells." (PMID 28222747, 2017).